XAF1 (XIAP associated factor 1)
Diseases named in the same sentence as XAF1 in open-access papers (continued):
Sharing a sentence is not in itself a finding about the gene and the disease.
glioma (continued). "Collectively, this study indicates that XAF1 plays a key role in TMZ cytotoxicity by directing apoptotic switch of protective autophagy through ROS–ATM–AMPK signaling, illuminating the mechanistic consequence of epigenetic inactivation of XAF1 in glioma pathogenesis." (PMID 35274103, 2022). "Furthermore, comparing CIMP-positive vs. CIMP-negative tumors, a 2.63-fold repression of mRNA expression and a 3.23-fold enhanced methylation of XAF1 was observed in the MSKCC cohort of lower grade glioma samples." (PMID 28122345, 2017). "Furthermore, MTM knockdown could markedly increase miR-873 expression, and reduce pGL3-XAF1 3' UTR luciferase activity and XAF1 expression in glioma cells treated with WZY-321." (PMID 35517406, 2022). "As a result, XAF1 might be a new potential target for glioma therapy." (PMID 35517406, 2022). "In this study, we observed that XAF1 induction by TMZ directs an apoptotic switch of protective autophagy, identifying XAF1 as a critical tumor suppressor that governs the glioma response to TMZ therapy." (PMID 35274103, 2022). "The studies showed that shXAF1 treatment not only reduced XAF1 expression but also reduced glioma cell apoptosis induced by WZY-321, indicating that WZY-321 lead to glioma cell apoptosis through up-regulating XAF1 expression." (PMID 35517406, 2022). "We analyzed XAF1 methylation in a panel of 16 GB cell lines and 80 patients with first-diagnosed WHO grade III/IV high-grade gliomas using methylation-sensitive high-resolution melt (MS-HRM) analysis." (PMID 28122345, 2017). "In a recent study on the methylation profile of the GB samples from the TCGA (The Cancer Genome Atlas), a significant down-regulation of XAF1 expression and hypermethylation was detected in G-CIMP proneural gliomas." (PMID 28122345, 2017). "Stratifying according to tumor histology revealed that the survival difference was specific for grade III gliomas (AA, AO and AOA) and suggested XAF1 methylation to be a prognostic marker for these tumor entities." (PMID 28122345, 2017). "Expression of ISGs MX1, XAF1, or OAS2 strongly correlated with MAP3K7 dependency in DepMap glioma lines and this correlation was still present, but weaker, in 930 non-glioma cell lines." (PMID 38632238, 2024). "Moreover, XAF1 transcription is activated by TMZ and its induction is a critical event responsible for glioma response to TMZ therapy." (PMID 35274103, 2022). "Since, it was predicted that miR-873 could bind to XAF1 3' UTR, the levels of miR-873 expression were determined in the cultured glioma cells after WZY-321 stimulation." (PMID 35517406, 2022). "As already mentioned, this could indicate that for long-term survival differences (as in glioma patients under TMZ therapy), the impact of XAF1 on cell cycle progression might play a predominant role." (PMID 28122345, 2017). "While we could provide evidence that XAF1 methylation is strictly (100%) linked to 2-HG-producing mutations in IDH1 (shown for R132H, R132G) in grade III gliomas, we were not able to identify a less frequent IDH2-mutant tumor within the data set." (PMID 28122345, 2017). "The luciferase analysis showed that WZY-321 treatment did not enhance XAF1 promotor activity in the glioma cells, suggesting that WZY-321 could increase XAF1 expression at posttranscriptional level in glioma cells." (PMID 35517406, 2022).
hepatocellular carcinoma (6 papers, 2007 to 2023). A malignant tumor that arises from hepatocytes. "For all the hepatoma and pancreatic cancer cells tested, XAF1 mRNA levels increased upon cell damage, which indicated a potency of cell apoptosis that was reasonable for chemoagent treatments." (PMID 37189754, 2023). "Nevertheless, a correlation between low XAF1 protein expression and progression of tumour stage and grade has also been reported in hepatocellular carcinomas, supporting a possible functional relevance of XAF1 down-regulation for the progression of various malignancies including ccRCCs." (PMID 19664236, 2009). "Blockade of miR-1976 could enhance chemosensitivities of hepatoma and pancreatic cancer cells in an XAF1-dependent manner, as evidenced by increased levels of cell apoptosis, reduced IC50 in cell toxicity assays, and suppressed tumor growth in animal xenograft experiments in vivo." (PMID 37189754, 2023). "XAF1 was expressed in the hepatoma HepG2 cells and pancreatic BxPC-3 cells but not in the hepatoma Hep3B cells and pancreatic AsPC-1 cells." (PMID 37189754, 2023). "Interestingly, after treatment of human hepatoma cells with a combination of IFN-α and IFN-γ, transcriptional induction of selective ISGs (including xaf1) was found to be dependent upon IRF-1." (PMID 17376236, 2007). "However, the role of XAF1 in hepatocellular carcinoma (HCC) remains unknown." (PMID 24980821, 2014).
prostate carcinoma (6 papers, 2010 to 2021). A carcinoma that arises from epithelial cells of the prostate gland. "A recent result showed that weak expression of XAF1 was associated with androgen deprivation resistance in prostate cancer." (PMID 24980821, 2014). "The varying expression of XAF1 suggests a causal changing of androgen dependency and invasiveness in the development of prostate cancer." (PMID 21143993, 2010). "Somatostatin and Octreotide up-regulate XAF1 mRNA and protein in all prostate cancer cell lines, but the underlying mechanisms need further investigations." (PMID 21143993, 2010). "It was shown that YY1 binds to XAF1 promoter and thereby inhibits its expression in prostate cancer cell lines in a HDAC1 dependent mechanism." (PMID 31824839, 2019). "YY1 inhibits XAF1 expression in prostate cancer cells lines through HDAC1 dependent mechanism and thereby induces cancer progression." (PMID 31824839, 2019). "Mechanistically, to promote prostate cancer growth, YY1 has been shown to repress the expression of X-linked inhibitor of apoptosis (XIAP) associated factor-1 (XAF1), a tumor suppressor in prostate cancer cells." (PMID 31824839, 2019). "Somatostatin and Octreotide up-regulated XAF1 mRNA and protein expression in all prostate cancer cell lines." (PMID 21143993, 2010). "In the current study, we examined XAF1 mRNA and protein expression in four cell lines, and determined regulatory effects of somatostatin and Octreotide on XAF1 expression in prostate cancer cell lines." (PMID 21143993, 2010). "The enhanced XAF1 expression by somatostatin indicates a promising strategy for prostate cancer therapy." (PMID 21143993, 2010). "We found that somatostatin and Octreotide up-regulated XAF1 mRNA and protein expression in prostate cancer cell lines." (PMID 21143993, 2010). "It is interesting to evaluate the potential regulatory effects of somatostatin on XAF1 expression during the development of prostate cancer cells." (PMID 21143993, 2010). "It has been demonstrated that in prostate cancer full‐length XAF1 might be downregulated while truncated isoforms are expressed." (PMID 33734579, 2021). "YY1 represses the tumor suppressor XAF1 and thereby promotes prostate cancer growth." (PMID 31824839, 2019). "Understanding the regulating effects of XAF1 during the whole progression may help us find potential therapeutic strategies for prostate cancer patients." (PMID 21143993, 2010). "The effects of somatostatin on the prostate cancer cells may be mediated by enhanced expression of XAF1 through its pro-apoptotic effect." (PMID 21143993, 2010). "Our findings suggest that XAF1 down-regulation may contribute to the prostate cancer development." (PMID 21143993, 2010). "XAF1 down-regulation may contribute to the prostate cancer development." (PMID 21143993, 2010). "Downregulation of the XAF1 transcript may occur during the development of prostate cancer." (PMID 21143993, 2010). "Cumulatively, pro-apoptotic genes, such as XAF1 and GADD45B were down-regulated, whereas DRAM1 was up-regulated in the adipose tissue of prostate cancer patients." (PMID 23009291, 2012). "We report, the first time, that somatostatin and Octreotide up-regulate XAF1 mRNA and protein expression in LNCaP, DU145 and PC3 prostate cancer cell lines." (PMID 21143993, 2010). "It showed lower expression of XAF1 mRNA in prostate cancer cells LNCaP, DU145 and PC3 compared with that in RWPE-1 cells which displayed the strongest expression of XAF1 mRNA among all four cell lines." (PMID 21143993, 2010). "Substantial levels of XAF1 mRNA and proteins were detected in RWPE-1 cells, whereas prostate cancer cells LNCaP, DU145 and PC3 exhibited lower XAF1 expression." (PMID 21143993, 2010).
bladder cancer (5 papers, 2009 to 2024). "Transfection assays with the 253J and HT1376 bladder cancer cell lines were performed to elucidate the relation between XAF1 gene expression and cell chemosensitivity." (PMID 39051186, 2024). "Considering that XAF1 has recently been reported to predict treatment response of bladder cancer patients to chemotherapy, it appears also reasonable to evaluate its predictive value in ccRCC patients as well." (PMID 19664236, 2009). "Collectively, these findings indicate that hnRNPK enhances bladder cancer cell anti‐apoptosis and chemoresistance to cisplatin by regulating XAF1 and ERCC4 and that it may be a potential target for drug development." (PMID 27862976, 2017).
breast carcinoma (4 papers, 2018 to 2025). "Breast cancer may be mildly influenced by co-segregation with XAF1 p.E134*, and this variant can also confer risk for sarcoma." (PMID 40558276, 2025). "Downregulation of the proapoptotic protein XIAP-associated factor 1 (XAF1), which counteracts XIAP inhibition, is observed in breast cancer cell lines and tissues." (PMID 38794316, 2024). "We also observed an inverse correlation of GRP78 and XAF1 expression in human cancer cell lines of various origins and primary breast carcinoma tissues." (PMID 35902580, 2022). "XAF1 and GRP78 expression show an inverse correlation in human cancer cell lines and primary breast carcinomas." (PMID 35902580, 2022).
colorectal cancer (4 papers, 2009 to 2021). A primary or metastatic malignant neoplasm that affects the colon or rectum. "The restoration of XAF1 expression has been shown to induce cell apoptosis in gastric and colorectal cancer cell lines and strengthen the apoptotic effects of chemotherapeutic drugs and TNF Related Apoptosis Inducing Ligand (TRAIL)." (PMID 24980821, 2014).
lung carcinoma (4 papers, 2016 to 2024). "In lung cancer cells, XAF1 tumor suppressor activity was decreased by BRD7 knockdown, and inhibition of tumor growth by IFN-γ did not appear in BRD7-depleted xenograft tumors." (PMID 26802028, 2016). "XAF1 increases sensitivity to IR in lung cancer cells, but its effect in lung cancer remains unclear." (PMID 26802028, 2016). "We tested the cellular effects of XAF1 expression in the human lung cancer cell line A549." (PMID 26802028, 2016). "Our microarray data analysis revealed and RT-qPCR confirmed the increased mRNA expression of all of the OAS gene family members (OAS1, OAS2, OAS3, OASL) and XAF1 and IRF7 in the lung cancer cell line A549 after transfection with BNC2." (PMID 28184177, 2017). "XAF1 decreased migration and invasion ability in lung cancer cells, although the increase in XAF1 expression, migration and invasion was not reduced by BRD7 depletion." (PMID 26802028, 2016). "To investigate whether BRD7 acts as critical regulator of XAF1 in lung cancer cells, we examined migration and invasion by transfecting BRD7 siRNAs into cells overexpressing XAF1." (PMID 26802028, 2016). "Unlike in HMVECs, XAF1 induced apoptosis in lung cancer cells." (PMID 26802028, 2016).
renal cell carcinoma (4 papers, 2009 to 2025). "Up-regulation of XAF1 protein expression augmented IFN-induced apoptosis, whereas down-regulation conferred protection from IFN-induced apoptosis in the renal cell carcinoma cell line ACHN." (PMID 19664236, 2009). "In renal cell carcinoma, down-regulation of CXXC4 by siRNA resulted in the up-regulation of some cellular proliferation related genes (FGF18, EGR1, and MYCN), the down-regulation of apoptosis inhibitor proteins BIRC7 and XAF1, and some other important tumor progression factors." (PMID 30042169, 2018).
sarcoma (4 papers, 2022 to 2025). A usually aggressive malignant neoplasm of the soft tissue or bone. "XAF1 induction of P-AMPK was also detected in multiple nonglioma cells, including IMR90 (fibroblast), T47D (breast), HCT116 (colon), and U2OS (sarcoma) and XAF1 depletion disrupted TMZ cytotoxicity in XAF1 expression subline of PC3 (prostate)." (PMID 35274103, 2022).
influenza infection (3 papers, 2011 to 2022). "Knockout of XAF1 attenuates host antiviral innate immunity in vitro and in vivo, which leads to more severe lung injuries and higher mortality in the influenza infection mouse model." (PMID 35972291, 2022). "Compared to the PBMCs from the healthy controls, higher expression of XAF1 mRNA was detected in the PBMCs from the moderate and severe influenza patients." (PMID 35972291, 2022). "However, XAF1 and ATF3 have no reported roles in response to influenza infection and thus represent valuable predictions for further investigation." (PMID 22074594, 2011).
liver cancer (3 papers, 2014 to 2021). An epithelial or non-epithelial malignant neoplasm that arises from the liver. "The expression levels of XIAP and XIAP-associated factor-1(XIF1) also positively correlated with survival in primary liver cancer patients." (PMID 27057629, 2016). "The low expression of XAF1 was linked to apoptosis resistance of liver cancer." (PMID 24980821, 2014). "The results suggest that constitutive overexpression of XAF1 inhibits cell proliferation of liver cancer cells." (PMID 24980821, 2014). "The weak expression of XAF1 has been shown to be associated with portal vein tumor thrombi (PVTT), preoperative AFP level, tumor size, and recurrence of liver cancer." (PMID 24980821, 2014). "Therefore, the restoration of XAF1 expression may be a new approach for liver cancer treatment." (PMID 24980821, 2014). "Western blot showed that XAF1 expression was lower in liver cancer tissues than that in the paired non-HCC tissues." (PMID 24980821, 2014). "We further determined the expression of XAF1 in 30 human liver cancer tissues and paired adjacent non-cancer liver tissues." (PMID 24980821, 2014). "Our results showed that XAF1 expression was lower in HCC cell lines SMMC-7721, Hep G2 and BEL-7404 and liver cancer tissues than that in paired non-cancer liver tissues." (PMID 24980821, 2014).
neuroblastoma (3 papers, 2007 to 2025). Neuroblastoma (NB) is the most common solid, extracranial childhood tumor. "Kinesin family member 1B beta (KIF1Bβ) and XIAP-associated factor 1 (XAF1) mediate apoptosis in neuroblastoma cells." (PMID 41189817, 2025). "However, the exact mechanism underlying XAF1 tumor suppression and the prospective therapeutic strategies involving XAF1 remain to be characterized in neuroblastoma." (PMID 27097110, 2016). "Overexpression of XAF1 impairs tumor progression whereas knockdown of XAF1 promotes tumor growth, suggesting that XAF1 may be a candidate tumor suppressor in neuroblastoma and its associated pathway may be important for developing future interventions." (PMID 27097110, 2016). "Improper alterations in downstream effectors of developmental apoptosis such as down-regulation of XAF1 may play a pathogenic role in neuroblastoma development by allowing neuronal progenitors to escape from developmental culling and thereby predisposing them to neoplastic transformation." (PMID 27097110, 2016). "Taken together, this suggests that XAF1 expression may be indicative for survival outcome and disease status, and treatments that restore XAF1 expression or its associated pathway may be a promising approach to overcome neuroblastoma." (PMID 27097110, 2016). "XAF1 is a potent antagonist of anti-apoptotic XIAP and Survivin whereby Survivin is associated with high-risk neuroblastoma." (PMID 27097110, 2016). "In summary, we provided evidence to demonstrate the tumor suppressive effect and prognostic potential of XAF1 in neuroblastoma." (PMID 27097110, 2016). "In this study, we investigated the expression of XAF1 as well as its role in tumor suppression and apoptosis induction in neuroblastoma." (PMID 27097110, 2016). "Here, we found that overexpression of XAF1 is sufficient to induce significant apoptosis in neuroblastoma." (PMID 27097110, 2016). "Taken together, these results demonstrate that XAF1 overexpression is sufficient to induce apoptosis in neuroblastoma cells in vitro." (PMID 27097110, 2016). "Taken together, these results suggest that XAF1 silencing protects against KIF1Bβ-mediated apoptosis and that XAF1 is necessary for KIF1Bβ apoptotic pathway in neuroblastoma cells." (PMID 27097110, 2016). "This was confirmed in neuroblastoma cells whereby XAF1 knockdown in the presence of KIF1Bβ resulted in resistance to KIF1Bβ-mediated apoptosis." (PMID 27097110, 2016). "Next, we examined the prognostic value of XAF1 expression using a tissue microarray (TMA) of human neuroblastomas, and performed survival analyses stratified by treatment status." (PMID 27097110, 2016). "To assess the effect of XAF1 overexpression on neuroblastoma tumor growth in vivo, we generated SK-N-SH neuroblastoma cells transduced with lentivirus to stably overexpress XAF1 as verified via Western Blot." (PMID 27097110, 2016). "According to TMA analysis, the median 5-year overall survival of all 86 patients is 73.3% (63 out of 86 cases) and majority of neuroblastomas (71 out of 86 cases) showed null or low (1+) expression of XAF1." (PMID 27097110, 2016). "Subsequently, XAF1 knockdown group showed a distinct increase in tumor growth rate compared to the control group, suggesting that XAF1 knockdown promotes neuroblastoma tumor growth in vivo." (PMID 27097110, 2016). "This reinforced the notion that upstream regulation of XAF1 by KIF1Bβ could be a relevant tumor suppression pathway in neuroblastoma." (PMID 27097110, 2016). "Consistent with our in vitro findings, these observations suggest that XAF1 plays an important role in tumor development whereby it may function as a tumor suppressor in neuroblastoma." (PMID 27097110, 2016). "To do so, we used a high XAF1-expressing CHP212 neuroblastoma cells." (PMID 27097110, 2016). "Together with our in vitro findings, our study suggests that XAF1 may function as a tumor suppressor in neuroblastoma." (PMID 27097110, 2016).